TNF (tumor necrosis factor)
Diseases named in the same sentence as TNF in open-access papers (continued):
Sharing a sentence is not in itself a finding about the gene and the disease.
tumor (continued). "These molecules can be administered intravenously or orally and upregulate IFN-β, TNF-α, and other cytokines in vivo, inhibiting tumor growth, promoting immune cell infiltration, and establishing antitumor immune memory." (PMID 41415288, 2025). "The activation of NF-κB is significantly increased in these cells, resulting in the secretion of cytokines such as IL6, TNFα, and IL1β, which subsequently promote cell proliferation and tumor viability." (PMID 40869207, 2025). "While curdione and borneol inhibited inflammatory factors such as IL-6 and IL-1β expression in macrophages, TNF-α and CASP1 mRNA expression levels were up-regulated, which are associated with anti-tumor and anti-viral responses." (PMID 39911394, 2025). "A comparative study has shown that tumor necrosis factor-α (TNFα), a known cytokine involved in all stages of the tumor malignant process, stimulates system y+-mediated L-arg uptake in saphenous and umbilical vein human ECs." (PMID 41295280, 2025). "The vitro studies have shown that mast cell-derived PGD2 regulates the tumor microenvironment by limiting excessive responses to vascular permeability and TNF-α production." (PMID 40474982, 2025). "This highlights another role for NF-κB, which is also involved in resistance to TNF-α–mediated apoptosis, further underscoring its multifaceted role in tumor cell survival and adaptation." (PMID 41335396, 2025). "The significant increase in IFN-α, IFN-γ,granulocyte-macrophage colony stimulating factor (GM-CSF), and TNF-α suggested a more effective anti-tumor effect in the combination group." (PMID 40469178, 2025). "This creates a feed‐forward loop: T cells expressing TNFRSF18 exhibited impaired TNF signalling, which compromised their ability to control highly stem‐like tumour cells and consequently accelerated immune evasion." (PMID 40770837, 2025). "This study aimed to explore the relationship between the presence of F. nucleatum and the expression of inflammation-related genes (IL6, IL1B, IL10, IL17, TNF) in tumor and matched normal tissue of Kazakhstani CRC patients." (PMID 41267807, 2025). "Heregulin inhibits TNFR1/NF-KB, activates caspase-3, reduces cell viability, and diminishes tumor size in TNF-a environments." (PMID 41584509, 2025). "Activated macrophages, T cells, various immune cells including natural killer cells, and even tumor cells produce TNF-α." (PMID 40558596, 2025). "For instance, biglycan activates Toll-like receptors (TLR4 and TLR2) on macrophages, promoting TNF-α and MIP-2/CXCL2 expression, which sustains tumor-associated inflammation." (PMID 41281748, 2025). "Curcumin has also been shown to enhance T-cell resistance to apoptosis by neutralizing oxidative stress in tumor cells, restoring NF-κB activity, and reactivating the TNF-α signaling pathway." (PMID 40940890, 2025). "These conditions can promote pro-inflammatory cytokine release (IL-1β, IL-6 and TNF-α), angiogenesis and tumor proliferation." (PMID 41395614, 2025). "This strategy promoted CD3+ T-cell recruitment into tumors, amplified pro-inflammatory cytokine levels (e.g., IFN-γ, TNF-α), suppressed tumor growth and metastasis, and prolonged survival in preclinical models." (PMID 41181137, 2025). "By increasing the secretion of tumor necrosis factor (TNF-α) and reducing the number of immunosuppressive cells such as myeloid-derived suppressor cells (MDSCs), Metformin can reshape the tumor immune micro-environment and promote tumor cell death." (PMID 40161377, 2025). "The role of TNF in cancer is controversial, but it is well described that at high concentrations it induces tumor regression and recruitment of immune cells through TME remodeling." (PMID 40107242, 2025). "Preclinical and clinical evidence indicates that combining cytokines with complementary mechanisms such as IL-2 with TNFα, IL-12, can produce synergistic immune activation and improved tumor control (48, 80; )?." (PMID 41568361, 2025).
tumor (continued). "This broad expression turns TNFR1 into a key focus in tumor studies, as its signaling can either promote cell survival or induce cell death depending on factors such as cell type, TNF dosage, and the recruitment of specific proteins to the receptor complex." (PMID 41315176, 2025). "They directly induce tumor cell apoptosis by releasing perforin and granzyme B, while concurrently secreting cytokines such as interferon-gamma(IFN-γ) and TNF-α to inhibit tumor proliferation and activate macrophages." (PMID 40977714, 2025). "Anti-TNF-α therapies, particularly monoclonal antibodies, have demonstrated promising effects in reducing inflammation and tumor progression, but the emergence of resistance mechanisms underscores the need for improved therapeutic strategies." (PMID 40558596, 2025). "The evolution of tumor immunology has marked a transformative era for cytokines, including tumor necrosis factor (TNF), interleukins (ILs), and interferons (IFNs)." (PMID 40075727, 2025). "Older adults exhibit persistent elevation of proinflammatory cytokines such as IL-6 and TNF-α, and impaired inflammation resolution mechanisms, which creates a pathological microenvironment that masks tumor-specific inflammatory signals." (PMID 40901675, 2025). "In contrast, cytokine analysis within the tumor microenvironment revealed a significant increase in TNF-α levels, which was further supported by elevated TNF-α gene expression." (PMID 40429884, 2025). "Initially identified for its ability to induce tumor cell apoptosis, TNF is now recognized as a key mediator of inflammation, contributing to both innate and adaptive immunity." (PMID 41304898, 2025). "In fact, TNF-α appeared to plateau in middle stages and then surge in Stage IV, suggesting that a substantial tumor burden or metastasis is required to provoke a marked systemic TNF-α response." (PMID 40299527, 2025). "This normalization interrupts calcium-dependent inflammatory signaling, curbing the production of pro-inflammatory cytokines such as TNF-α and IL-6, thereby further reducing the pro-inflammatory milieu within the tumor microenvironment." (PMID 40243559, 2025). "Here, we found that Rgs2+CD8+ T cells had the potential of cytokine secretion, such as IFN‐γ and TNF, to activate other immune cells involved in the anti‐tumor response." (PMID 40586324, 2025). "The results suggest a favorable evolution of our patients, considering the role of TNF-α in stimulating tumor progression." (PMID 40564098, 2025). "Tumor necrosis factor inhibitors (TNFis) not only exhibit anti-inflammatory and anti-tumor effects but also promote tumor growth by inhibiting apoptosis." (PMID 40725854, 2025). "CD8+ T cells exert direct cytotoxic effects on cell surfaces through “ligand-receptor” interactions, and they participate in cellular immunity against tumor cells by producing cytokines, tumor necrosis factor, and interferon-alpha." (PMID 40356925, 2025). "The main mechanism involves the activation of HIF-1α or oncogenes (such as RAS) by hypoxia or inflammatory factors (such as IL-6 and TNF-α) in the tumor microenvironment, leading to the secretion of VEGF, mainly VEGF-A." (PMID 40438141, 2025). "Preliminary studies have shown that nanoparticles carrying TNF-α inhibitors or IL-6 blockers can localize treatment to the tumour site, thereby increasing the therapeutic window while reducing toxicity." (PMID 40544399, 2025).
tumor (continued). "In CRC, higher TM4SF4 expression is associated with liver metastasis, worse survival, tumor development and epithelial-mesenchymal transition (EMT) program regulated by TGFβ/Snail, TNFα/NFκB, and thymidylate synthase pathways." (PMID 39999090, 2025). "Serum cytokines, such as TNF-α, IL-6, and IL-10, reflect inflammation and the tumor microenvironment." (PMID 41226541, 2025). "Among them, cytokines such as IFN-γ and TNF-α are key biomarkers produced by tumor-infiltrating T cells." (PMID 40944197, 2025). "Cancer cells escape TNF-α-induced death by releasing soluble TNF receptors (sTNFR1/2), which neutralize TNF-α and promote tumor survival via reverse signaling." (PMID 40868199, 2025). "Treatment with trastuzumab induces repolarization of M2 to M1 macrophages, promoting an anti-tumor immune response through the release of pro-inflammatory cytokines such as tumor necrosis factor (TNF)-α and interleukin (IL)-6." (PMID 41400702, 2025). "The association between TNF-α and tumor growth has been reported across various tumor types, due to the role of TNF-α in promoting tumor cell survival, proliferation, and the creation of an immunosuppressive microenvironment that fosters tumor progression." (PMID 39923035, 2025). "SASP components, including IL-6, IL-8, TNF-α, and MMPs, are secreted in tumor microenvironments and can be detected in blood or saliva samples." (PMID 41463272, 2025). "This study defines novel molecular subtypes of HCC and reveals that HPX exerts anti-tumor effects through TNF-α-mediated mitochondrial apoptosis, characterized by an increased Bax/Bcl-2 ratio." (PMID 41008813, 2025). "The bright red color indicates that the EAC group exhibited elevated levels of inflammatory markers (TNF, IL-1β, NF-κB), tumor markers (CA19, CA125, CA15), and oxidative stress indicators (MDA)." (PMID 41011277, 2025). "We also analyzed the expression of M1 markers (IL‐1β, Nos2, TNFα) and M2 markers (Arg‐1, CD206, IL‐10) in tumor‐associated macrophages." (PMID 39791593, 2025). "Bystander killing of TAA‐negative tumor cells has been reported to involve tumor necrosis factor (TNF) and IFNγ." (PMID 40178291, 2025). "GSEA showed many pathways were similarly enriched across mdTAM_2/3, mdTAM_4 and rTAM in anti-PD-L1-treated tumours, including ‘TNFα signaling via NFκB’ and ‘Inflammatory response’." (PMID 40523200, 2025). "The discovery of protein engineering has developed TNF-α fusion proteins with better tumor specificity and lower systemic toxicity, presenting new options for more effective, safer treatment." (PMID 40309351, 2025). "The results showed that IRFA significantly up-regulated TNF-α and IL-6 at the residual tumor site by 31-fold and 28-fold compared with NC, respectively." (PMID 39882403, 2025). "TNF-α also triggers proinflammatory and procoagulant responses in endothelial cells, thereby promoting tumor cell migration, invasion, and metastasis via NF-κB signaling." (PMID 40558596, 2025). "This analysis highlighted the consistent induction of pro-inflammatory cytokines such as IL-1β, IL-6, IL-8, IL-10, IL-17A/F, and TNF, which are known to play central roles in immune activation, macrophage polarization, and tumor–immune cell crosstalk." (PMID 41514627, 2025). "Further, a Bio-Plex immunoassay detected higher levels of IFN-γ as well as TNF-α in the lung microenvironment of tumor-bearing Tgfbr2MyeKO mice as compared to control mice (Supple fig." (PMID 40568095, 2025). "On one hand, certain subsets, such as human Vγ9Vδ2 T cells and murine Vγ1 and Vγ4 T cells, exert antitumor effects by secreting cytokines like IFN-γ and TNF-α and directly mediating tumor cell cytotoxicity." (PMID 41055972, 2025). "Such tissue-specific dysregulation aligns with UBD’s induction by pro-inflammatory cytokines like IFN-γ and TNF-α, suggesting its role as a molecular nexus between chronic inflammation and tumor progression." (PMID 41347086, 2025).
tumor (continued). "Its absence can reverse exhaustion, restoring CD8+ T-cell effector functions (e.g., IFN-γ, TNF-α) by 2-3-fold and reducing tumor burden by 50%." (PMID 41415289, 2025). "The interaction between macrophages and tumor cells triggers the release of proinflammatory cytokines such as tumor necrosis factor (TNF), interleukin-1 (IL-1), and interleukin-6 (IL-6), which contribute to endothelial damage and cell detachment." (PMID 40034639, 2025). "The activation of TLR2/TLR4 by HSPs causes the activation of HSF1 signaling followed by NF-kB signaling in DCs, resulting in the release of cytokines (IL-1, IL-6, and TNF) and the release of tumor antigens, which can be processed by APCs." (PMID 41375025, 2025). "In most tumor models, TNF-α acts primarily as an upstream factor, upregulating HMGCR transcription and activity through the NF-κB/SREBP-2 pathway." (PMID 41450917, 2025). "Cytokines such as TNF-α, IL-1β, IL-2, and IL-6 can enhance tumor growth, angiogenesis, metastasis, and invasion by promoting the survival and proliferation of tumor cells through activation of the NF-κB pathway." (PMID 40172365, 2025). "Pro-inflammatory M1 macrophages release inflammatory mediators such as IL-6, TNF-α, and iNOS, inciting robust pro-inflammatory immune responses that inhibit tumor cell proliferation." (PMID 40670983, 2025). "Various reports provide significant evidence that TNF-α / TGF-β1 also regulates several receptor elements of the signaling mechanism in the tumor microenvironment in an interrelated manner." (PMID 40622490, 2025). "They influence cancer progression by modulating the MIF and TNF pathways, directly promoting tumor growth." (PMID 40136652, 2025). "A CRISPR screen has identified genes involved in IFNγ and TNFα signaling as critical mediators of CD8+ T cell‐mediated tumor cell killing." (PMID 40178291, 2025). "Several inflammatory mediators, including interleukins (IL-6, IL-8, IL-10), tumor necrosis factor (TNF), and chemokines (CXCL12, CXCR4), are implicated in tumor progression and the pathological inflammatory microenvironment of these tumors." (PMID 40433410, 2025). "M1 macrophages exert anti-tumor effects by activating T cells through the release of cytokines such as interleukin-12 (IL-12) and TNF-α." (PMID 40098971, 2025). "We first compared the responses of tumor cells in CD8 T cell (herein referred to as T cell) co-culture to those in direct TNF stimulation." (PMID 41315176, 2025). "Remarkably, we elucidated the role of the NF‐κB and TNF‐α pathways in mediating immunotherapy resistance within the immune‐enriched tumor microenvironment." (PMID 40859961, 2025). "Th1 cells produce pro-inflammatory cytokines such as IFN-γ and tumor TNF-α, which are involved in immune responses against infections but can also contribute to inflammation and tissue damage if not properly regulated." (PMID 39859499, 2025). "TNF-α exhibited cytoplasmic and perinuclear staining in both tumor and immune cells, with more prominent expression in tumor-infiltrating immune cells." (PMID 41259576, 2025). "In this model, serine/glycine deprivation significantly reduced tumor-reactive T cell cytotoxic activity and the expression of key T cell effector cytokines, including IL-2, TNF, and IFNγ." (PMID 40389477, 2025). "Conversely, higher FSS suppressed tumor cell motility, possibly by stimulating macrophage secretion of cytotoxic or anti-migratory mediators such as TNF-α, IL-1β, or reactive species." (PMID 41439943, 2025). "Specifically, BRD4 was shown to maintain the active form of NF-κB in tumors, while BET inhibition broadly sensitized diverse tumor cell lines to the cytotoxic activity of TNF, involving the suppression of pro-survival NF-κB transcription." (PMID 40858106, 2025). "These interrelated events synergize to stimulate osteoclast differentiation, trigger bone resorption, and facilitate the release of TNF and IL-6, thereby promoting tumor metastasis." (PMID 39816691, 2025).
tumor (continued). "For instance, IFN-γ and TNF stabilize the p16INK4a-Rb pathway, promoting tumor cell senescence and dormancy." (PMID 40292253, 2025). "The results revealed significant upregulation of IFN-γ and TNF-α, pro-inflammatory cytokines known to play crucial roles in anti-tumor immunity." (PMID 39979981, 2025). "In vivo studies demonstrated that palonosetron reduced tumor growth and modulated pro-inflammatory cytokines—tumor necrosis factor alpha, interleukin 6, and interleukin 1β." (PMID 41155333, 2025). "Our observation that TNF-α is highest in metastatic (Stage IV) disease and correlates with markers like CA19-9 fits this paradigm: as the tumor burden increases, TNF-α levels rise, potentially aiding processes like tumor spread and immune evasion." (PMID 40299527, 2025). "NF-κB is activated by proinflammatory factors such as TNF-α and IL-1 and, in the tumor microenvironment, can drive both proinflammatory responses and, under certain conditions, be reprogrammed to support tumor cell survival and proliferation." (PMID 41002423, 2025). "In animal models, dihydroartemisinin outperformed cisplatin by enhancing body mass and substantially decreasing serum TNF-α concentrations, tumor mass, and volumetric dimensions with 41.45% tumor growth inhibition." (PMID 41001347, 2025). "To confirm the exhausted status of CD8+ T cells following co-culture with MC38 tumor cells, we also assessed the expression of cytotoxic molecules and cytokines, including granzyme B, and tumor necrosis factor-alpha (TNF-α)." (PMID 40799645, 2025). "• Inhibited TNF-α-induced activation of NF-κB.• Reduced colon tumorigenesis by 36%.• Decreased tumor surface area by 31% (at 0.04% δT3-13'-COOH diet).• Suppressed multiplicity of total polyps by 25% and large polyps by 54%." (PMID 39181121, 2025). "Of note, non-classical monocytes are considered the primary monocyte population involved in the anti-cancer response, secreting tumor necrosis factor α (TNF-α) and IL-12 upon interaction with tumor cells." (PMID 41440002, 2025). "As for B cells, neutrophils can promote tumor immune escape by secreting TNF‐α, which binds to CXCL13 or CXCL12 and mediates B cell chemotaxis." (PMID 40979214, 2025). "Macrophage-released cytokines, including IL-1 and TNF-α, induce the expression of Upp1 in tumor cells." (PMID 41243973, 2025). "The decline in TNF-α likely results from diminished tumor burden and consequent reduction in chronic inflammation." (PMID 40977702, 2025). "Encoded by SPP1, OPN reshapes the tumor immune microenvironment by inducing M2-like TAM polarization, suppressing dendritic cell migration, and promoting Th1 responses via IL-12 and TNF-α." (PMID 40895569, 2025). "In vivo studies showed that treatment with BB-NVs increased the proportion of CD3+CD4+ and CD3+CD8+ cells in tumor tissue and spleen and significantly increased the expression of anti-tumor cytokines TNF-α, IL-6, IL-10, and IFN-γ." (PMID 40284501, 2025). "Pro-tumor cytokines like IL-10 and TGF-β promote an immune-evasive environment, while antitumor cytokines like IL-2 and TNF-α strive to elicit immune-mediated tumor destruction." (PMID 40309351, 2025). "Research suggests that Infliximab can suppress H. pylori–induced upregulation of CXCR4 by inhibiting TNF-α signaling, thereby reducing GC cell migration and exhibiting anti-tumor potential." (PMID 41376630, 2025). "FcγRI‐CAR‐HMs treatment shifted tumor‐associated macrophages (TAMs) from an immunosuppressive to immunostimulatory phenotype, evidenced by upregulated CD86/IL‐1β/IL‐12/TNF‐α and downregulated CD206/TGF‐β." (PMID 40847445, 2025). "BAT within the mediastinum secretes adipokines such as leptin and pro‐inflammatory cytokines (e.g., IL‐6, TNF‐α), which promote tumor cell proliferation, angiogenesis, and immune evasion." (PMID 40755324, 2025). "For example, inflammatory factors such as TNF‐α and IL‐6 promote tumor cell invasion and metastasis by activating the epithelial–mesenchymal transition pathway." (PMID 41267926, 2025).